TAOK1 (TAO kinase 1)
Description:
Serine/threonine-protein kinase involved in various processes such as p38/MAPK14 stress-activated MAPK cascade, DNA damage response and regulation of cytoskeleton stability. Phosphorylates MAP2K3, MAP2K6 and MARK2. Acts as an activator of the p38/MAPK14 stress-activated MAPK cascade by mediating phosphorylation and subsequent activation of the upstream MAP2K3 and MAP2K6 kinases. Involved in G protein-coupled receptor signaling to p38/MAPK14. In response to DNA damage, involved in the G2/M transition DNA damage checkpoint by activating the p38/MAPK14 stress-activated MAPK cascade, probably by mediating phosphorylation of MAP2K3 and MAP2K6. Acts as a regulator of cytoskeleton stability by phosphorylating 'Thr-208' of MARK2, leading to activate MARK2 kinase activity and subsequent phosphorylation and detachment of MAPT/TAU from microtubules. Also acts as a regulator of apoptosis: regulates apoptotic morphological changes, including cell contraction, membrane blebbing and apoptotic bodies formation via activation of the MAPK8/JNK cascade. Plays an essential role in the regulation of neuronal development in the central nervous system. Also plays a role in the regulation of neuronal migration to the cortical plate (By similarity).
Synonyms: hKFC-B; MARKK; PSK-2; PSK2; hTAOK1; KIAA1361; MAP3K16; FLJ14314; TAO1; DDIB; KFC-B
Tractability: Small molecule: a high-quality ligand is known; it belongs to a druggable protein family. Antibody: its Gene Ontology location is reachable by antibodies, with high confidence. PROTAC: ubiquitination databases record sites on it; its protein half-life has been measured; a small molecule that binds it is known.
Target class: STE protein kinase STE20 family; Enzyme; Kinase; STE protein kinase group; STE protein kinase TAO subfamily; Protein Kinase
Chemical probes: TAO Kinase inhibitor 1 (high quality)
Gene: Protein-coding gene on chromosome 17 (29,390,351 to 29,551,903, forward strand). Ensembl gene ENSG00000160551.
Subcellular location: Cytoplasm
Subcellular location (Human Protein Atlas): Cytosol; Plasma membrane; Primary cilium; Vesicles
Pathways (Reactome):
Cell Cycle: Amplification of signal from unattached kinetochores via a MAD2 inhibitory signal; EML4 and NUDC in mitotic spindle formation; Mitotic Prometaphase; Resolution of Sister Chromatid Cohesion; Separation of Sister Chromatids
Disease: Dengue virus modulates apoptosis
Signal Transduction: RHO GTPases Activate Formins
Gene Ontology:
Molecular function: alpha-tubulin binding; beta-tubulin binding; kinase activity; protein binding; ATP binding; protein kinase activity; protein serine/threonine kinase activator activity; protein serine/threonine kinase activity; tau protein binding; tau-protein kinase activity; transferase activity; protein serine kinase activity
Biological process: central nervous system neuron development; DNA damage response; execution phase of apoptosis; microtubule cytoskeleton organization; mitotic G2 DNA damage checkpoint signaling; negative regulation of microtubule depolymerization; neuron cellular homeostasis; positive regulation of JNK cascade; positive regulation of stress-activated MAPK cascade; regulation of actin cytoskeleton organization; regulation of cytoskeleton organization; regulation of microtubule cytoskeleton organization
Cellular component: cytosol; extracellular exosome; microtubule cytoskeleton; perinuclear region of cytoplasm; cytoplasm
Genetic constraint (gnomAD): Loss-of-function variants: 14 observed, 101.49 expected, observed/expected ratio (o/e) 0.14, 90% interval 0.09 to 0.22. The upper end of that interval is the gene's LOEUF score, 0.22, which puts it in group 1 of 6, group 1 being the genes least tolerant of losing a copy. Missense variants: 557 observed, 1,093.6 expected, observed/expected ratio (o/e) 0.51, 90% interval 0.47 to 0.55. Synonymous variants: 309 observed, 360.42 expected, observed/expected ratio (o/e) 0.86, 90% interval 0.78 to 0.94.
Gene-disease validity (ClinGen):
ClinGen rates the evidence that TAOK1 causes each of these diseases.
syndromic intellectual disability (autosomal dominant): Definitive. A intellectual disability that is part of a larger syndrome.
Homologues: Orthologues: macaque TAOK1 (99% identical), dog TAOK1 (99% identical), pig TAOK1 (99% identical), rabbit TAOK1 (99% identical), mouse Taok1 (99% identical), rat Taok1 (99% identical), guinea pig TAOK1 (95% identical), tropical clawed frog taok1 (90% identical), chimpanzee TAOK1 (89% identical), zebrafish taok1a (85% identical), zebrafish taok1b (84% identical). Paralogues in human: TAOK3 (66% identical), TAOK2 (59% identical), SLK (25% identical), TNIK (24% identical), MAP4K4 (23% identical), STK10 (22% identical), MINK1 (22% identical), NRK (20% identical), MAP4K3 (19% identical), MAP4K5 (18% identical), MAP4K2 (18% identical), MAP4K1 (17% identical), and 23 more.
Diseases named in the same sentence as TAOK1 in open-access papers:
TAOK1 is named in the same sentence as 60 diseases in open-access papers, as found by Europe PMC text mining. Sharing a sentence is not in itself a finding about the gene and the disease. The quoted sentences say what the papers report.
breast carcinoma (5 papers, 2012 to 2026). "TAOK1-CRYBA1 was identified based on the rationale that TAOK1 upregulation is related to the oncogenic potential in malignancies such as breast cancer." (PMID 32825119, 2020). "TAOK1 is upregulated in a group of breast cancer and found fused in breast cancer cell lines." (PMID 32825119, 2020). "The thousand and one (TAO) kinases, TAOK1, TAOK2, and TAOK3, have garnered great interest for their role in, and therapeutic potential for, breast cancer, neurodegeneration in human tauopathies, and a large number of neurodevelopmental disorders (NDDs)." (PMID 41530942, 2026). "Several of the genes involved are also in signalling pathways relevant to breast cancer: ERBB2, NRIP1 and BCAS3 are involved in estrogen receptor function and APPBP2 with androgen receptor; while TAOK1 and SKAP1 are involved in MAPK signalling and DEPDC6/DEPTOR regulates mTOR signalling." (PMID 23260012, 2012). "For example, PHF20L1, BCAS3, TAOK1, PCGF2, and TRPS1 are fused in other breast cancers." (PMID 23260012, 2012). "Several of the fused genes are also recurrently broken in a substantial proportion of breast cancers, as judged by copy number steps in array-CGH of 1000 breast tumours: around 10% have breaks in ERBB2, BCAS3 and SKAP1, while COL14A1, TIAM1, USP32, TAOK1 are broken in around 4%." (PMID 23260012, 2012).
lung carcinoma (4 papers, 2022 to 2023). "Evidence has revealed that TAOK1 might function as a Hippo pathway gene and is the main element of the susceptibility of lung cancer cells." (PMID 36158126, 2022). "In the lung carcinoma cell line H1299, it was found that the activation of TAOK1 can induce cell contraction, membrane blebbing, cleavage of Rho kinase 1 and caspase 3, and activate the JNK pathway to induce apoptosis." (PMID 38136890, 2023). "The results suggested that increased expression of TAOK1 in lung cancer tissues showed high levels relative to lung tissues." (PMID 36158126, 2022). "However, several interesting fusions were identified in multiple samples, including TAOK1-PIPOX and LPIN2-MYOM1, which were each found in 3 samples and have been observed previously in breast and lung cancer TCGA datasets, respectively." (PMID 36675685, 2022).
developmental delay (3 papers, 2021 to 2022). "A rare de novo microdeletion at 17q11.2, which covers TAOK1, was identified in a patient with a developmental delay and postnatal microcephaly, suggesting a possible role of TAOK1 to contribute to NDDs." (PMID 33867937, 2021). "In addition, the TAOK1 gene was associated with OMIM disease (developmental delay with or without intellectual impairment or behavioral abnormalities, MIM #619575) starting from 19 October 2021." (PMID 35928450, 2022). "However, the authors noted that, in some cases, developmental delay maybe very mild, whereas behavioral issues and distinctive facial dysmorphisms such as frontal bossing, downslanting palpebral fissures, long philtrum, and bulbous nasal tip are widely common among TAOK1 carriers." (PMID 34768579, 2021).
gastric cancer (3 papers, 2016 to 2024). A primary or metastatic malignant neoplasm involving the stomach. "In gastric cancer, miR-941 was also observed to be downregulated, possibly targeting KDM6B and TAO kinase 1 (TAOK1) to inhibit cell proliferation, migration and invasion." (PMID 32742479, 2020).
hepatocellular carcinoma (3 papers, 2016 to 2025). A malignant tumor that arises from hepatocytes. "We also found decreased proliferative, migratory, and invasive capacity, as well as lower epithelial-mesenchymal transition in TAOK1-deficient human hepatoma-derived cells." (PMID 36930872, 2023). "Migration, invasion, and epithelial-mesenchymal transition were examined in TAOK1-deficient human hepatoma-derived cells." (PMID 36930872, 2023). "Several studies have demonstrated that TAOK1 possesses oncogenic properties in non-small cell lung cancer (NSCLC), hepatocellular carcinoma (HCC), and ESCC." (PMID 40003990, 2025). "The levels of TAO kinase 1, which activates p38 MAPK cascades and is a potential therapeutic target for cancers with defective β-catenin signalling such as hepatocellular carcinoma, were significantly up-regulated." (PMID 27443843, 2016).
viral infection (3 papers, 2021 to 2025). "To gain a deeper understanding of the functionality of TAO kinases in the context of virus infection, we applied full proteomic analysis using SFV-infected wild-type (wt) and TAOK1, -2, or -3 KO THP-1 cells." (PMID 34853303, 2021). "Furthermore, a TAOK1 knockdown assay in KYSE510, KYSE140, and KYSE150 cells using lenti-virus infection was conducted." (PMID 40003990, 2025). "Interestingly, many of the candidate proteins have only limited functional links to viral infection and immune regulation and were not previously known to interact with NAs (e.g., c8orf88, DTYMK, KIF2A, PDAP1, PDIA5, TAOK1, TAOK2, and VRK1)." (PMID 34853303, 2021).
vitiligo (3 papers, 2021 to 2024). Generalized well circumscribed patches of leukoderma that are generally distributed over symmetric body locations and is due to autoimmune destruction of melanocytes. "Previous study identified that microRNA-211 and its target genes (e.g. RRM2, TAOK1) regulated oxidative phosphorylation and energy metabolism and represented potential therapeutic targets for vitiligo." (PMID 34603063, 2021). "In addition, putative target genes of miR-211 such as PPARGC1A, RRM2, and TAOK1 are highly upregulated in Vitiligo, which is a pigmentation disorder." (PMID 39409187, 2024).
Alzheimer disease (2 papers, 2020 to 2024). A progressive, neurodegenerative disease characterized by loss of function and death of nerve cells in several areas of the brain leading to loss of cognitive function such as memory and language. "Abnormalities in TAOK1 have also been associated with the progression of autism and Alzheimer's disease." (PMID 38664915, 2024). "Perhaps a more interesting ontological category is the 11 downregulated genes associated with MAPK signaling pathway, a number of which (Arrb2, Cacna1g, Fgfr4, Taok1, Cacna1h) have been implicated in Alzheimer's disease (AD)." (PMID 33282900, 2020).
autism (2 papers, 2022 to 2024). Persistent deficits in social interaction and communication and interaction as well as a markedly restricted repertoire of activity and interest as well as repetitive patterns of behavior. "During the revision of the manuscript, the definitive classification of the gene-disease relationship between TAOK1 and syndromic intellectual disability was curated by the ClinGen Intellectual Disability and Autism Gene Curation Expert Panel on 4 August 2021." (PMID 35928450, 2022).
Hepatic fibrosis (2 papers, 2016 to 2022). The presence of excessive fibrous connective tissue in the liver. "Furthermore, the injection of miR-706 antagomir promoted liver fibrosis characterized by increased α-SMA and Col1 expression, associated with high PKCα and TAOK1 expression." (PMID 27876854, 2016). "We further investigated the molecular mechanisms of miR-706 in liver fibrosis using bioinformatics indicating that PKCα and TAOK1 might be targeted genes regulated by miR-706." (PMID 27876854, 2016). "In addition, we demonstrated that PKCα and TAOK1 are direct targets of miR-706 in hepatocytes responsible for EMT during liver fibrosis." (PMID 27876854, 2016).
ischemic stroke (2 papers, 2019). A stroke disorder caused by obstruction of blood flow to the brain, due to thrombotic (local blood clot formation) or embolic (due to a blood clot or other material traveling from another site) event. "c) mmu-miR-199a-5p and mmu-miR-199b-3p regulated the Taok1 gene to inhibit the inflammatory response during the recovery phase of ischemic stroke and exert neuroprotective effects." (PMID 31681398, 2019). "The underlying mechanism revealed the involvement of PI3K/AKT and MAPK signaling pathway in the protective effects of TAOK1 in ischemic stroke." (PMID 31652447, 2019). "In terms of the mechanism, the PI3K/AKT and MAPK signaling pathways were involved in the induction of TAOK1 effects in ischemic stroke." (PMID 31652447, 2019). "We then performed TAOK1 gain- and loss-of functions in the oxygen-glucose deprivation (OGD) induced in vitro neural stem cell model of ischemic stroke." (PMID 31652447, 2019). "In the present study, we aimed to investigate the roles of TAOK1 in ischemic stroke." (PMID 31652447, 2019). "However, whether TAOK1 plays a role in the pathogenesis of ischemic stroke still remains unclear." (PMID 31652447, 2019). "We initially examined the expression of TAOK1 in middle cerebral artery (MCA) occlusion (MCAO) rat model, which is the most frequently used animal model of ischemic stroke." (PMID 31652447, 2019). "TAOK1 expression was significantly down-regulated, however, IL-1β, IL-6 and IL-8 expression were up-regulated in MCAO rat model and OGD-induced neural stem cell model of ischemic stroke." (PMID 31652447, 2019). "In addition, we demonstrated that TAOK1 expression was significantly decreased in the MCAO rat model and OGD-induced cell model of ischemic stroke when compared with sham-operative rats and normal neutral stem cells, respectively." (PMID 31652447, 2019).
melanoma (2 papers, 2024 to 2025). A malignant, usually aggressive tumor composed of atypical, neoplastic melanocytes. "In this study, LINC01198 is identified highly upregulated and acts as driving factor, which associates with TAOK1/TAOK2 to activate Hippo pathway and transcriptionally induce IL-1B expression for supporting melanoma resistance against vemurafenib." (PMID 41145465, 2025). "Mechanistically, LINC01198 associates with TAOK1/2 to attenuate their phosphorylation and following enzymatic cascade, which potentiates nuclear transportation of YAP/TAZ to transcriptionally promote IL1B expression and enhance the viability of melanoma cells treated with vemurafenib." (PMID 41145465, 2025). "Mechanistically, LINC01198 directly associates with TAOK1/2 to inhibit TAOK1/2 phosphorylation and thereby elicits Hippo signaling through TAOK/LATS axis, which redistributes YAP/TAZ into nucleus and promotes the expression and secretion of IL-1β to support vemurafenib resistance in melanoma." (PMID 41145465, 2025).
Neurodevelopmental delay (2 papers, 2023 to 2025). "A recent study demonstrated that missense de novo variants in TAOK1 cause neurodevelopmental delays in children." (PMID 36800380, 2023).
chordoma (1 paper, 2022). Chordomas are rare malignant tumors arising from embryonic remnants of the notochord in axial skeleton. "Five regulators of this pathway (TAOK1, TAOK2, MOB1A/B, and LATS1) were significantly suppressed in chordoma samples and two of them are predicted targets for upregulated miRNAs (TAOK1 for miR-142, and MOB1B for miR-148a and miR-182)." (PMID 36033338, 2022).
clear cell renal cell carcinoma (1 paper, 2022). "TAOK1 is associated with overall survival in clear cell renal cell carcinoma." (PMID 36217201, 2022).
colitis (1 paper, 2022). Inflammation of the colon. "Thousand and one kinase 1 (TAOK1) could as a negative regulator of IL-17 to mediate signal transduction and inflammation, controlling colitis of inflammatory bowel disease." (PMID 35012443, 2022).
colorectal adenocarcinoma (1 paper, 2025). The most common type of colorectal carcinoma. "As a negative regulator of IL-17-mediated signaling and inflammation, TAOK1 shows markedly reduced expression in the colonic tissues of patients with ulcerative colitis and colorectal adenocarcinoma." (PMID 41465457, 2025).
colorectal cancer (1 paper, 2022). A primary or metastatic malignant neoplasm that affects the colon or rectum. "Meanwhile, overexpression of TAOK1 was uncovered in colorectal cancer tissues." (PMID 36158126, 2022).
growth disorders (1 paper, 2024). "As well as the gene TAOK1 in muscle, which in humans is related to muscle hypotonia and growth disorders, and in a previous GWAS study in pigs, it has been pointed as a candidate gene associated with the number of mummified Landrace animals." (PMID 38992576, 2024).
hepatoblastoma (1 paper, 2023). Hepatoblastoma (HB) is a malignant hepatic tumor and is the most common pediatric liver cancer. "The tumor suppressive genes (Taok1, Lats1, Nf2), upstream of the Hippo pathway that inhibit YAP through phosphorylation-induced cytoplasmic retention and degradation, are important for hepatoblastoma proliferation." (PMID 37414763, 2023).
heterotopia (1 paper, 2024). "We provide a clinical description of a child with a neurodevelopmental disorder due to a novel TAOK1 truncating variant, whose brain magnetic resonance imaging displays periventricular nodular heterotopia." (PMID 38443934, 2024).
liver steatosis (1 paper, 2023). "STE20-type kinase TAOK1 has been identified as a component of hepatocellular LD proteome, suggesting a potential role in regulating liver steatosis and NAFLD development." (PMID 36930872, 2023). "We observed a positive correlation between the TAOK1 mRNA abundance in human liver biopsies and key hallmarks of NAFLD (i.e., hepatic steatosis, inflammation, and ballooning)." (PMID 36930872, 2023). "We observed that TAOK1 mRNA expression in human liver biopsies was positively correlated with the key hallmarks of NAFLD (ie, hepatic steatosis, inflammation, and ballooning) and TAOK1 protein abundance was increased in livers from high-fat diet-fed mice compared with lean controls." (PMID 36930872, 2023).
myocardial infarction (1 paper, 2024). Gross necrosis of the myocardium, as a result of interruption of the blood supply to the area, as in coronary thrombosis. "The overexpression of MiR-199a-3p could also stimulate cardiomyocyte proliferation and cardiac regeneration after myocardial infarction by binding to TAOK1 and activating YAP." (PMID 39457531, 2024).
neuroblastoma (1 paper, 2013). Neuroblastoma (NB) is the most common solid, extracranial childhood tumor. "In human neuroblastoma cells, Taok1 transfection induces apoptosis." (PMID 23472202, 2013).
neuronal migration disorders (1 paper, 2024). "Literature reports lack evidence of neuronal migration disorders in TAOK1 patients, although studies in animal models suggest this possibility." (PMID 38443934, 2024).
non-alcoholic steatohepatitis (1 paper, 2024). "Consequently, our research has substantiated through a comprehensive series of cellular, animal, and molecular assays that lincRNA00907 exacerbates the progression of non-alcoholic steatohepatitis (NASH) via the miR-942-5p/TAOK1 axis." (PMID 38613803, 2024).